IL6 (interleukin 6)
Diseases named in the same sentence as IL6 in open-access papers (continued):
Sharing a sentence is not in itself a finding about the gene and the disease.
depression (continued). "RCTs are needed to test whether manipulation of IL-6 signalling has an impact on depressive symptoms in individuals with depression, but such studies are lacking." (PMID 30244217, 2018). "Interestingly, the highest concentration of IFN-α induces up to 5 pg/mL of IL-6, a concentration similar to that found in both plasma and CSF of HCV patients who developed IFN-α-induced depression, and this is the concentration of IL-6 that we use in our in vitro experiments." (PMID 29040650, 2018). "The major findings of this study are that peripheral, but not brain, IL-6 has an important role in the depression-like phenotype after social defeat stress and that gut microbiota may have a role in the antidepressant effects of anti-IL-6 receptor MR16-1." (PMID 28556833, 2017). "The aim of this study was to determine whether individuals with depression display differential methylation of the IL6 gene promoter compared to individuals without depression." (PMID 29070016, 2017). "Consequently, medications that result in lower IL-6 and TNF-α level might have a direct positive impact on treating depression." (PMID 30886949, 2017). "Increased IL-6 and TNF-α levels may promote depression by downregulating serotonin metabolism." (PMID 28930237, 2017). "Increased IL-6 and TNF-α levels may also promote depression by downregulating serotonin metabolism." (PMID 28930237, 2017). "Moreover, we observed that 3 of 8 depression rats regarded as ketamine non-responder group displayed lower serum levels of IL-1β and IL-6." (PMID 28600519, 2017). "Interestingly, the baseline Beck Depression Inventory-II scores correlated positively with changes in IL-6 levels over the follow-up period, but not with changes in CRP levels." (PMID 27918465, 2016). "However, IL6 genotype did not moderate the effects of non-interpersonal stress exposure (i.e., financial, work and health-related difficulties) on depression." (PMID 25596176, 2015). "The majority of major depressive patients included in our meta-analysis could be classified as severely or very severely depressed; IL-6, CRP and TNF-α were more strongly associated with severe than non-severe forms of depression." (PMID 26065825, 2015). "It seems that medication-free depressed patients may exhibit a unique profile in which activation of particular pro-inflammatory cytokines (especially that of IL-6) and reductions of growth factors (especially that of BDNF) are inversely related to the severity of depression." (PMID 23675319, 2013). "At this time there is ample reason to suggest that particular cytokines (e.g., IL-6) and growth factors (e.g., BDNF) might serve as biomarkers in predicting who would be most prone to depression under various challenge conditions, and which treatment strategies would be most efficacious." (PMID 23675319, 2013). "In a recent review of the connection between depression and inflammation, Krishnadas pointed out that a third of patients with major depressive disorder (MDD), without any other major illness, have elevated inflammatory biomarkers; in particular, CRP, TNF-α, and IL-6." (PMID 23898306, 2013). "For the total sample, regardless of diagnosis, IL-6 correlated to level of depression (P < 0.01)." (PMID 22830048, 2012). "However, it has to be mentioned that in our study there was a trend in increasing levels for TNFα and a trend in decreasing levels for IL-6 in perimenopausal women with depression when compared to perimenopausal women without depression." (PMID 22490187, 2012). "We also found a significant correlation between CIS-induced behavior changes and pro-inflammatory cytokines (IL-6 and TNF-á) and monoamines (5-HT, 5-HIAA and DA), indicating that elevated levels of pro-inflammatory cytokines may function in the development of depression." (PMID 22860054, 2012).
depression (continued). "Moreover, in patients with major depressive disorder (MDD), the presence of high levels of pro-inflammatory cytokines (in particular IL-6) and acute phase proteins suggest that inflammatory mediators might contribute to the pathophysiology of depression even in the absence of medical illness." (PMID 19423079, 2009). "For GF the following 5 variables were entered: depression, muscle torque, % predicted FEV1, end SpO2, IL 6; for PF: depression, ISWT, % predicted FEV1 and age; for RA: depression, ISWT, % predicted FEV1 and BMI; for RM: depression, end Borg RPE and end SpO2 and for MF: depression, IL6 and end SpO2." (PMID 19845947, 2009). "However, this study did not investigate whether IL-6 mediated this response to improve depression symptoms." (PMID 40843259, 2025). "Therefore, CRP may be more strongly related to depressive symptoms in the context of major depression, whereas other inflammatory molecules, such as IL-6, may be related to depressive symptoms regardless of whether someone is presently experiencing depression." (PMID 40357904, 2025). "Chronic inflammation, with raised levels of pro-inflammatory cytokines such as IL-6 and TNF-α, and C-reactive protein (CRP), affect the central nervous system—specifically, dopaminergic function in the basal ganglia, which may result in depression, fatigue, and cognitive and motor slowing." (PMID 40487528, 2025). "Consequently, this stimulation could result in elevated levels of inflammatory biomarkers in patients with both cancer and depression compared to those without depression, as evidenced by IL‐6 concentrations." (PMID 40387308, 2025). "Elevated pro-inflammatory cytokines like interleukin-6 (IL-6), interleukin-1β (IL-1β), and tumor necrosis factor-alpha (TNF-α) have been consistently observed in women with PPD, further supporting the inflammatory hypothesis of depression and the involvement of the MGB axis." (PMID 41293186, 2025). "As IL-1β release can initiate microglia and astrocyte activation leading to the downstream synthesis of other proinflammatory cytokines in CNS (e.g., IL-6), the chronic microglial activation reported in depression may activate a negative feedback to supress IL-1β." (PMID 40179065, 2025). "Moreover, a rodent depression model, showed a lack of increased IL-1β but elevation of IL-6, similar to our results in the human DLPFC, strongly indicating that studies are required to identify how IL-1β level changes in the brain with ageing and its subsequent effects." (PMID 40179065, 2025). "Because IL-6, and companion pro-inflammatory cytokines, participate in the initiation, progression, spread and recurrence of cancer, minimally invasive VNS could be employed to suppress glioma or cancer progression, while also mitigating depression and/or seizures, thereby enhancing quality of life." (PMID 39512605, 2024). "The downregulation of HDC expression led to the activation of the IL-6/STAT3/S100A9 pathway, stimulating Th17 cells to secrete IL-17A, thereby promoting ovarian cancer progression, which suggests that HDC may be a potential therapeutic target for the comorbidity of ovarian cancer and depression." (PMID 39720595, 2024). "Depression and anhedonia were significantly improved in patients with MDD, while the IL-6 did not significantly change after the FLV treatment." (PMID 37304432, 2023). "One hundred eight nonclinical participants with various levels of anxiety/depression underwent magnetic resonance imaging scans during an emotional face task for amygdala activity and saliva collection (at 10-time points across 2 days) for the total output and diurnal patterns of interleukin-6." (PMID 37324818, 2023). "Several systemic reviews and meta-analysis studies on the correlation between cytokines level and depression, anxiety, and PTSD showed evidence of higher levels of IL-1, IL-6, and TNF-α in individuals with Major Depressive Disorder (MDD), anxiety, and PTSD compared to controls." (PMID 37388279, 2023).
depression (continued). "The node degrees of IL6, nitric oxide synthase 3 (NOS3), solute carrier family 6 member 4 (SLC6A4), estrogen receptor (ESR1), and tumor necrosis factor (TNF) were greater than 10, suggesting that these targets could play important roles in the effects of AL on depression." (PMID 36431060, 2022). "Furthermore, in an LPS-induced rat model of depression, administration of ketamine and GTS-21([3-(2,4-dimethoxybenzylidene) anabaseine], a selective α7 nAChR agonist) was shown to reduce the levels of IL-1β, IL-6, and TNF-α compared to the group of rats treated with LPS alone." (PMID 34948222, 2021). "Thus, increases in plasma IL-6 and to a lesser extent CRP have been found in elderly individuals taking care of a spouse with a chronic medical condition, persons with a low socioeconomic, victims of childhood abuse or maltreatment and patients with depression in comparison to respective controls." (PMID 30769887, 2019). "Therefore, immune dysregulation in depressive disorders does not involve exclusively pro-inflammatory cytokines, such as IL-6 and TNF-α, but also activation of anti-inflammatory cytokines, which may result in positive treatment outcomes." (PMID 31375659, 2019). "Inflammation is unlikely to be relevant for all patients with depression, so consideration is required regarding the choice of suitable patients and outcomes for clinical trials of anti-inflammatory treatment to elucidate potential mechanistic role of the IL-6 system in depression (below)." (PMID 30244217, 2018). "Surprisingly, the authors did not identify elevated levels of IL-6 in depressed women compared to control women nor a positive correlation between IL-6 and depression severity, although there is a great body of literature showing IL-6 to be elevated in depression." (PMID 28848457, 2017). "Proinflammatory cytokines, such as TNF-a, IL-1, and IL-6, are the major mediators between the brain, HPA axis, and immune system and continuous prolonged upregulation of proinflammatory cytokines can lead to depression and HPA axis suppression, which may trigger exacerbation of asthma." (PMID 28740537, 2017). "While studies of depression support the hypothesis that increases in inflammation result in decreased BDNF and attenuated neuroplasticity, we report decreases in both peripheral BDNF and inflammatory factors (although there is a trend for elevated IL-6 in CSS F2 females)." (PMID 34055816, 2016). "Finally, we do not have repeated measures of inflammatory cytokines (IL-6, ACT and CRP) and therefore could not analyse whether long-term exposure to high levels of inflammatory markers are associated with depression." (PMID 25877654, 2016). "However, it is not clear how IL6 impinges on neurotransmission and thus contributes to depression." (PMID 25760924, 2015). "In addition, based on the fact that cytokines could have large influence on the HPA axis, evidence on the increase of cytokines such as interleukin 1 (IL-1), interleukin 6 (IL-6) and tumor necrosis factor alpha (TNF-α) among the patients with depression and anxiety may further support this theory." (PMID 26222511, 2015). "Consistent with the suggestion that violent and/or impulsive behaviors may be linked to neuropsychiatric conditions, increased IL-1β, IL-6, and TNF-α in post-mortem PFC were observed in teenaged individuals that died by suicide, irrespective of whether they had been diagnosed with major depression." (PMID 25565946, 2014). "Parenthetically, even though the available data point to the fundamental involvement of IL-6 in relation to depressive illnesses, this should not be taken to mean that other cytokine variations, especially those that occur in the brain, are not relevant to the evolution of depression." (PMID 23675319, 2013). "In clinical populations, IL-6, IL-1β, and CRP were elevated among women with depression, whereas these markers were not elevated in men, and rather men displayed elevated levels of IL-17." (PMID 40305313, 2025).
depression (continued). "A study from Poland found significantly higher levels of both IL-6 and CRP in study participants with depression than in those without." (PMID 38575920, 2024). "Similar to our results, the authors report that patients with T2DM and comorbid depression had elevated levels of CRP and IL-6 compared to those diabetic subjects without depression." (PMID 39409133, 2024). "Regarding BPD, the findings are not so consistent; in a clinical trial, it was found that IL-6 levels were not different from controls, while in another study in BPD patients comorbid with major depression, increased IL-6 have been found compared to controls." (PMID 38654728, 2024). "Compared to individuals without depression, those with depression had a higher fat mass index (FMI (β = 0.48, 95% CI 0.22–0.74)) and increased blood levels of fibroblast growth factor 21 and Interleukin-6 in early adulthood." (PMID 39523673, 2024). "Higher levels of pro-inflammatory markers such as CRP, IL-6 and TNF-α and more fatigue are seen in patients with depressive disorders because of negative effects on the nervous system." (PMID 38297218, 2024). "In humans, the levels of pro-inflammatory cytokines IL-1β, IL-6, and TNF-α were reported to be significantly higher in the post-mortem brains of suicided patients with depression than in those of matched non-psychiatric controls." (PMID 37273278, 2023). "This was most notable in subjects who experienced a clinically significant improvement in depression where they had significant decreases in IL‐6, CRP, and tumor necrosis factor alpha (TNF‐α) compared to those who experienced no improvement in depression." (PMID 36178333, 2023). "In our results, cancer patients with depression exhibited higher levels of inflammatory cytokines (IFN-γ, TNF-α, and IL-6), as compared to the cancer patients without any depression." (PMID 37153524, 2023). "Moreover, a recent study revealed that the serum level of sIL-6R, but not IL-6 or TNF-α, is significantly associated with the pathogenesis of the treatment-resistant major depressive disorder, suggesting that IL-6 trans-signaling may be involved in the onset of this disease." (PMID 37187893, 2023). "The difference between IL-6 and IL-10 levels in women with and without HDRS score-based depression was not statistically significant." (PMID 37840785, 2023). "There is ample evidence to support the association between increased cortisol and pro-inflammatory cytokines (IL-1β, IL-6, IL-8, TNF-α) in negative mood conditions, stress levels, anxiety, and depression." (PMID 36986501, 2023). "The difference between IL-6 and IL-10 levels in women with and without EPDS score-based depression was not statistically significant." (PMID 37840785, 2023). "Clinical evidence has demonstrated significantly higher concentrations of inflammatory cytokines, such as IL-1β, IL-6 and TNF-α activated by NLRP3 in the cerebrospinal fluid and serum of patients with depression compared to non-depressed individuals." (PMID 37474898, 2023). "Plasma concentrations of stress and inflammatory biomarkers (cortisol, CRP, IL-6 and TNF-α) have been found to be increased in patients with major depressive disorder who have a history of treatment non-response, compared to treatment-responsive patients." (PMID 36648973, 2023). "Only one article associated the number of depressive episodes with inflammatory factors (IL-6), but not with BDNF or with the presence of previous episodes of depression." (PMID 35740389, 2022). "Compared to depressed men, depressed women have higher levels of IL-6, after controlling for BMI, and in a study of 231 men and women with major depressive disorder, higher CRP levels correlated with severity of depression in women but not men." (PMID 36304737, 2022). "Again, they found an increase in plasma levels of IL-1β, IL-6, and IL-17 in MDD MS patients (n=20) compared to MS patients without depression (n=20)." (PMID 36189272, 2022).
depression (continued). "In support of this concept of heterogeneity in MDD, a recent study found distinct immunologic profiles for inflamed and non-inflamed depression, with the inflamed group characterized by increased levels of circulating neutrophils, monocytes, CD4+ T cells along with elevated IL-6 and CRP." (PMID 35332134, 2022). "In agreement with our results, an interventional study showed that supplementation with vitamin D (50,000 IU 2wks−1) for eight weeks did not decrease serum IL-6 and hs-CRP concentrations in adult subjects with depression." (PMID 36368945, 2022). "In a recent study in a mouse model of depression, CBD reduced both serum and prefrontal cortex IL-6, but not TNF-α,12 h after LPS administration." (PMID 33984046, 2021). "including patients with major depressive disorder, only hs-CRP predicted an improvement on TMT-A, but not the cytokine IL-6." (PMID 34877553, 2021). "This negative result is discordant with several studies and meta-analyses showing higher levels of some immune factor in patients with depression compared to non-depressed controls, such as C-reactive protein (CRP), IL-6, and TNF-alpha." (PMID 34741019, 2021). "In subjects with depression, the level of TNF-α and IL-6 had a negative correlation with the number of EPC." (PMID 34421539, 2021). "Neither the logIC IL-6, logEC IL-10, and logIC TNF-α values at baseline, follow-up, nor their overall courses significantly correlated with depression severity scores or course measured by the BDI-II or the HAMD (data not shown)." (PMID 33447872, 2021). "IL-7 is tentatively higher in participants with a primarily somatic subtype at baseline, while IL-6 and SAA decrease over time in those with a somatic but not cognitive subtype of depression." (PMID 33276697, 2020). "Finally, these findings accord with the growing consensus that TNFα, IL-6 and CRP are among the important biomarkers with translational potential in mood disorders, suggesting that this may be true in the psychological as well as pharmacological treatment of depression." (PMID 33276697, 2020). "The correlation with the reduction of depression symptomatology we observed for TNF-α, IL-6, and IL-10 levels is not fully consistent with the reported alterations of these cytokines after antidepressant treatment according to most recent meta-analyses." (PMID 31375659, 2019). "Levels of BDNF, hsCRP, IL-6 and TNF-α are able to discriminate either euthymia or depression by being no different in that mood phase in comparison with levels in controls but altered in other mood phases." (PMID 30113291, 2018). "Levels of IL-6, CRP and other markers of systemic inflammation appear to be higher in MS patients reporting symptoms of depression compared with patients who do not report such symptoms." (PMID 29294244, 2018). "Hitherto, no meta-analysis has specifically compared the peripheral levels of proinflammatory markers including IL-1β, IL-6, TNF-α and CRP between elderly with depression or Alzheimer’s disease and controls without any psychiatric disorder." (PMID 30104698, 2018). "Meta-analyses have demonstrated that IL-6, TNF, and CRP are elevated in non-cancer patients with depression disorder." (PMID 30266081, 2018). "In this study, we observed increased levels of proinflammatory cytokines of IL-6, IL-1β, TNF-α as well as anti-inflammatory cytokines of IL-4 and IL-10 in the rats with depression-like phenotype, but not rats without depression-like phenotype." (PMID 28600519, 2017). "Rats with depression-like phenotype displayed higher serum levels of IL-1β, IL-6 and TNF-α than rats without depression-like phenotype (P < 0.05)." (PMID 28600519, 2017). "Even though there are studies showing that people with depression have elevated levels of inflammatory biomarkers, such as TNF-alpha, IL-6, and CRP, inflammation is not necessary or sufficient for the diagnosis of depression." (PMID 26451727, 2015).